SPTBN1 (spectrin beta, non-erythrocytic 1)
Diseases named in the same sentence as SPTBN1 in open-access papers (continued):
Sharing a sentence is not in itself a finding about the gene and the disease.
cancer (continued). "We firstly analyzed expression patterns and prognostic landscapes of SPTBN1 in human cancers using various databases and web-based tools." (PMID 37013511, 2023). "With cancer metastasis progressing, the expression level of SPTBN1 was further increased and the pro-cancer effect was gradually amplified." (PMID 37013511, 2023). "Subsequently, SPTBN1 expression in different grades/stages of TCGA cancers were explored by using UALCAN platform." (PMID 37013511, 2023). "On the other hand, we applied a Cox regression analysis to evaluate the prognostic value (OS, DSS and PFI) of SPTBN1 expression across TCGA cancers." (PMID 37013511, 2023). "A more comprehensive pan-cancer based on human solid adenocarcinoma is obviously needed to confirm this distinct biological manner of SPTBN1 in the future." (PMID 37013511, 2023). "Firstly, we used the TIMER2.0 online platform to explore the mRNA expression pattern of SPTBN1 across TCGA cancers." (PMID 37013511, 2023). "Here, we collected 47 common immune modulator genes, and analyzed the correlations between SPTBN1 expression and expression of these immune modulator genes across TCGA cancers (revised_Supplementary File 2 and revised_Figure 6 A)." (PMID 37013511, 2023). "It has meaningful to explore the relationships between SPTBN1 expression and common immunomodulator genes in cancers." (PMID 37013511, 2023). "Of interest were the associations with ANKRD30A, SPTBN1, and GALNTL5, as these genes have known and well-defined cancer associations." (PMID 33672646, 2021). "More recently, SPTBN1 has been reported to be abnormally expressed in several types of malignant tumor." (PMID 32699531, 2020). "Cancer Therapy: Blocking toxic SPTBN1 cleavage or enhancing its regulatory interactions (e.g., with SETD7 or autophagy pathways) could suppress HCC progression." (PMID 40301996, 2025). "We divided the cancer patients into high-SPTBN1 expression and low-SPTBN1 expression groups based on the median expression level of SPTBN1 and explored the correlation of SPTBN1 expression with the prognosis of patients with KIRC and UVM from the TCGA database using Kaplan-Meier plotter." (PMID 37013511, 2023). "We selected SPTBN1 as a subunit of the spectrin complex because of its involvement in cancer." (PMID 38069214, 2023). "The findings from current report demonstrated for the first time that when facing different types or grades/stages of human cancers, such as KIRC and UVM, SPTBN1 could serve as a dual-marker for predicting cancer prognosis and response of anti-cancer therapy." (PMID 37013511, 2023). "Relevance of SPTBN1 biological function and molecular mechanism in pan-cancer have been largely underexplored and the role of SPTBN1 in cancer development could be paradoxical and might vary among different types or stages/grades of cancers." (PMID 37013511, 2023). "But, the exact role of SPTBN1 in pan-cancer is still unclear." (PMID 37013511, 2023). "Importantly, these findings shed light on understanding the potential role of SPTBN1 in cancer immunity." (PMID 37013511, 2023). "Thus, we prepared this study to explore the prognostic and immunological role of SPTBN1 in pan-cancer, especially in KIRC and UVM." (PMID 37013511, 2023). "Thus, we explored relationships between SPTBN1 and 47 common types of immunomodulator genes in TCGA cancers (revised_Suppmentary File 2)." (PMID 37013511, 2023). "These speculations and GO findings may help explain contradictory roles of SPTBN1 in different kinds of cancers." (PMID 37013511, 2023). "Finally, our pan-cancer analysis discovered that SPTBN1 was significantly down-regulated in the tissue samples of most cancer subtypes, compared to that in adjacent normal samples." (PMID 36527113, 2022). "In this regard, the role of SPTAN1 and SPTBN1 in pathologies such as cancer has been reported." (PMID 35563422, 2022). "The SPTBN1-ALK fusion gene may be a biomarker for refractory cancer and a target for antitumor therapy." (PMID 33390831, 2021).
cancer (continued). "This increases the possibility of SPTBN1 as a biomarker for cancer diagnosis and prognosis." (PMID 33390831, 2021). "Furthermore, SPTBN1 expression is reduced in early stage CRC and that of Smad4 in advanced carcinomas, which indicates a key role for SPTBN1/Smad4/TGF-β signaling in the suppression of cancer progression." (PMID 31186638, 2019). "Hence, SPTBN1 is a potential candidate immunomodulatory factor and immunotherapy target in cancer." (PMID 37013511, 2023). "However, whether SPTBN1 could exert different roles and mechanisms in cancer development for different cancer types or stages still need additional experiments to prove it." (PMID 37013511, 2023). "Through searching literatures in PubMed database, we could not find any literature associated with pan-cancer analysis of SPTBN1." (PMID 37013511, 2023). "Similarly, SPTBN1 is downregulated in HCC and loss of its expression stimulates Wnt signaling, thereby promoting the acquisition of stem cell-like characteristics, and eventually, contributing to the growth of malignant tumors." (PMID 36905477, 2023). "Therefore, in the selection of treatment methods, the new SPTBN1-ALK fusion gene may be a potential target for anti-cancer therapy." (PMID 33390831, 2021). "Therefore, different regulations at transcriptomics levels or post-translational modifications may tune SPTBN1 expression from benign state to cancer progression." (PMID 33383671, 2020). "Interestingly, many of the DMGs identified had multiple roles and several were potential cancer biomarkers or were previously shown to be implicated in various types of cancers, including ABLIM1, ADAM12, ARHGEF4, FBLN2, ITGA6, LRPAP1, Ly9, NT5E, PITPNC1, PLCG1, OBSCN, RHOH, SPTBN1, SPOCK2 and SPRY1." (PMID 41159936, 2025). "Taken together, these results strongly demonstrate that in different kinds of cancers, such as KIRC and UVM, SPTBN1 can serve as a multifaceted indicator with different prognostic value." (PMID 37013511, 2023). "Thus, it still remains unclear whether SPTBN1 could be regarded as a friend or woe in pan-cancer." (PMID 37013511, 2023). "Following this, the prognostic value and cancer immunological role of SPTBN1 in KIRC and UVM were validated in our cancer patients and GEO database." (PMID 37013511, 2023). "Other candidates, such as the SPTBN1, NSD3 and CDK14 genes, are able to influence cancer progression through Wnt signaling." (PMID 30102725, 2018). "The current study presented compelling evidence that SPTBN1 might be a novel prognostic and therapy-related biomarker in KIRC and UVM, shedding new light on anti-cancer strategy." (PMID 37013511, 2023). "Moreover, we also found that SPTBN1 was potentially involved in the resistance of immunotherapy in KIRC, and the enhance of anti-cancer targeted treatment in UVM." (PMID 37013511, 2023). "The relationships between SPTBN1 expression and immune infiltration in cancers could be positive or negative depending on the types of tumors." (PMID 37013511, 2023). "However, the exact function of SPTBN1 in cancer progression and therapy has not been well-studied and still need further illumination." (PMID 37013511, 2023). "Nonerythrocytic spectrin beta 1 (SPTBN1) is an important cytoskeletal protein that involves in normal cell growth and development via regulating TGFβ/Smad signaling pathway, and is aberrantly expressed in various cancer types." (PMID 37013511, 2023). "These correlations were independent of human HCC stage, suggesting that the downregulation of SPTBN1 and the upregulation of IL-1α, IL-1β and IL-6 occur in HCC throughout all stages of cancer progression, and also irrespective of human hepatitis virus status." (PMID 33754058, 2021). "Whereas SPTBN1 was reduced, SPTAN1 expression was increased in moderately invasive and poorly differentiated CRC compared to nonpolyposis cancer cell lines." (PMID 31186638, 2019).
infection (3 papers, 2013 to 2023). The state of being infected such as from the introduction of a foreign agent such as serum, vaccine, antigenic substance or organism. "We found that IL-27-induced MDMs resist infection with HIV-1, and demonstrated that the resistance was associated with the down-regulation of spectrin beta, non-erythrocytic 1 (SPTBN1) or the induction of autophagy." (PMID 37910521, 2023).
neurodevelopmental disorder (3 papers, 2022 to 2026). A behavioral and cognitive disorder with onset during the developmental period that involves impaired or aberrant development of intellectual, motor, or social functions. "Missense and pLoF variants in SPTBN1 were recently implicated in a neurodevelopmental disorder; this variant was therefore classified as pathogenic." (PMID 40836029, 2026). "One of the pLoF variants was found in a gene previously linked to a neurodevelopmental disorder: the stop-gain in SPTBN1 (c.A520T; p.R174X) in proband MEGS_14 with persistent stuttering." (PMID 40836029, 2026). "According to prior literature on the genes implicated by our de novo analyses, none of the patients with neurodevelopmental disorders caused by mutations in SPTBN1, PRPF8, TRIO, and ZBTB7A have been described to stutter." (PMID 40836029, 2026). "Replication in a person who stutters is required to confirm that stuttering is a feature of the monogenic neurodevelopmental disorders associated with mutations in SPTBN1, PRPF8, TRIO, and ZBTB7A, and to causally link FLT3 and IREB2 to neurodevelopmental disorders." (PMID 40836029, 2026). "Previously, we developed a successful framework to prioritise gene candidates for neurodevelopmental disorders using mouse phenotyping data, with two of the top nine candidate genes, VPS4A and SPTBN1, having been recently validated." (PMID 36229886, 2022). "Exome sequencing analysis yielded a pathogenic variant in SPTBN1 as well as likely pathogenic variants in PRPF8, TRIO, and ZBTB7A - four genes previously implicated in neurodevelopmental disorders with or without speech problems." (PMID 40836029, 2026).
neurologic disorders (2 papers, 2022 to 2023). "The first 3 β-spectrin genes (SPTBN1, SPTBN2, and SPTBN4) are responsible of multiple neurologic disorders, depending on the gene and inheritance pattern." (PMID 36331550, 2023). "Variants in the spectrin genes SPTAN1, SPTBN1, SPTBN2, and SPTBN4 have been associated with neurological disorders; however, SPTBN5 gene-variants have not been associated with any human disorder." (PMID 35782384, 2022). "In addition, mutations in various members of the spectrin gene family are associated with erythroid cell disorders (SPTA1, SPTB) and neurological disorders (SPTAN1, SPTBN1, SPTBN2, and SPTBN4); however, no human genotype-phenotype correlation has been established for SPTBN5 to date." (PMID 35782384, 2022).
kidney diseases (1 paper, 2025). "We measured serum anti-SPTBN1 and anti-CBX3 IgA levels in patients with IgAN (n = 119) and other kidney diseases (disease control [DC], n = 51) using 2 independent cohorts, 1 from Japan and 1 from the UK." (PMID 40485707, 2025).
SPTBN1 also shares sentences with these, for which no sentence is quoted: nonalcoholic steatohepatitis (3 papers); atherosclerosis (2); breast tumors (2); depression (2); HIV-1 infection (2); rheumatoid arthritis (2); viral infection (2); adenoma (1); Alzheimer disease (1); Anxiety (1); anxiety disorder (1); Asperger syndrome (1); Ataxia (1); autism spectrum disorder (1); brain disorder (1); Burkitt lymphoma (1); cardiac hypertrophy (1); cardiovascular disease (1); Cerebral atrophy (1); colon adenocarcinoma (1); Crohn's colitis (1); cystic fibrosis (1); deafness (1); experimental autoimmune encephalomyelitis (1); fibroblastic disorder (1); gastric cancer (1); heart failure (1); hyperactivity attention-deficit/hyperactivity disorder (1); kidney failure (1); kidney tumors (1).
A further 16 diseases each share a sentence with SPTBN1 in 1 paper.